KDM5B (lysine demethylase 5B)
Diseases named in the same sentence as KDM5B in open-access papers (continued):
Sharing a sentence is not in itself a finding about the gene and the disease.
cancer (continued). "On a separate note, KDM5B has been demonstrated to be abundantly enriched in a variety of cancers." (PMID 38842683, 2024). "Moreover, our study demonstrated that KDM5B is associated with WNT/β-catenin signaling in the cytoplasm, HGF signaling in cancer, sphingolipid metabolism, and the Hippo pathway." (PMID 39239542, 2024). "Taken together, these findings showed that both KDM5A and KDM5B might act as protumorigenic factors in cancer, highlighting their potential as targets for therapeutic intervention." (PMID 39239542, 2024). "However, KDM5B is upregulated in various cancers, and possibly through its effects on the level and distribution of H3K4me3 near the promoters of cancer-related genes." (PMID 38769556, 2024). "KDM5B functions as an oncogene to regulate multiple malignant behaviors of cancer cells." (PMID 38842683, 2024). "Here, we demonstrate that KDM5B promotes PDAC cancer cells stemness and drug resistance." (PMID 38789418, 2024). "KDM5B also remodels cancer cell metabolism to promote BC progression." (PMID 38769556, 2024). "Phenotypically, KDM5B promotes cancer stem cells, DNA repair, EMT, and intratumoral heterogeneity." (PMID 38769556, 2024). "However, each KDM5 member has individual cancer implications and different binding patterns have been reported for KDM5B and KDM5C." (PMID 36631623, 2023). "Moreover, KDM5B is thought to modulate the expression of tumor-suppressing genes and oncogenes, thus affecting cancer cell proliferation." (PMID 37185734, 2023). "Interestingly, ETV, beyond its antiviral activity, acts as an inhibitor of KDM5B; therefore, it has the potential to become a valuable drug in the fight against cancer, so ETV can be repurposed, as demonstrated in silico studies." (PMID 38004468, 2023). "This ambivalence could be explained by the expression of KDM5B protein isoforms with diverse functional roles, which could be present at different levels in various cancer cell lines." (PMID 36697763, 2023). "The residue K242 is also ubiquitinated by the E3 ubiquitin ligases TRAF6 and/or SKP2, suggesting that KDM5B protein levels may be differentially regulated by synchronization of the ubiquitination and sumoylation machinery in cancers." (PMID 36697763, 2023). "Lysine-specific demethylase 5B (KDM5B) represses the expression of genes transcriptionally by erasing the methyl group from H3K4me2/3 and serves as an oncogene and associates with human cancers closely." (PMID 35333349, 2022). "Mounting evidence indicates that KDM5A and KDM5B are oncogenic and overexpressed in cancer." (PMID 35805040, 2022). "Although the functional ambiguity of KDM5A and KDM5B may slow the development of effective inhibitors, their diverse functions underscore their potential as cancer biomarkers and drug targets." (PMID 36509829, 2022). "Additionally, unveiling the molecular mechanism behind the ambiguous roles of KDM5A and KDM5B will act as a basis for the development of personalized treatment methods for patients with cancer and other diseases." (PMID 36509829, 2022). "A vast number of preclinical studies have shown the potential of KDM5A and KDM5B as therapeutic targets, and further investigations aiming to develop specific inhibitors for these proteins will facilitate the treatment of various diseases, including cancer." (PMID 36509829, 2022). "Additionally, the heterogenic roles of KDM5A and KDM5B in different cancers and developmental stages make optimization of these inhibitors difficult." (PMID 36509829, 2022). "The role of KDM5B in controlling radio-resistance in cancers, especially in ESCC remains quite unknown." (PMID 35333349, 2022). "However, contrary to PIAS1 and PIAS3, PIAS4 favors the survival of cancer cells, promoting the overexpression and stability of lysine demethylase 5B (KDM5B) in hypoxia through its sumoylation, thus provoking the inhibition of CDKN1A (P21) transcription." (PMID 35887358, 2022).
cancer (continued). "KDM5B was also identified as a regulator of cancer stem cell properties in oral cancers." (PMID 35899196, 2022). "Targeting SUMOylation-dependent KDM5B upregulation might be considered when the antiangiogenic therapy was applied in cancer treatment." (PMID 34977006, 2021). "Given the dependency of hypoxia adaption on KDM5B upregulation, targeting KDM5B might be an ideal strategy to overcome hypoxia adaption of cancer cells under anti-vascular treatment." (PMID 34977006, 2021). "The expression of KDM5B was much higher in cancer tissues than normal tissues." (PMID 34977006, 2021). "Targeting SUMOylation-dependent KDM5B upregulation might be considered when antiangiogenic therapy was applied in cancer treatment." (PMID 34977006, 2021). "Additionally, JIB-04 can increase the H3K4me3 level by inhibiting the expression of the methyltransferase KDM5B, thereby increasing the sensitivity of cancer cells to radiotherapy." (PMID 34385569, 2021). "Given that KDM5A and KDM5B expression are often affected in human cancer, we next investigated whether KDM5A and KDM5B expression participate in the management of drug-induced replication stress." (PMID 34184733, 2021). "Indeed, the KDM5B protein is the target of various inhibitors that are under study for the treatment of cancer." (PMID 33854980, 2021). "Moreover, KDM5A and KDM5B participate in radioresistance since their depletion sensitizes cancer cells to DNA damages induced by radiation or radiomimetic compounds." (PMID 34184733, 2021). "Among them, KDM5B has been reported to be relevant in multiple human cancers including GC." (PMID 34977006, 2021). "Interestingly, Kdm5b deletion in the mouse prostate leads to mild hyperplasia, which is surprising given its reported pro-oncogenic role in prostate and other cancers." (PMID 33245716, 2020). "Therefore, the development of specific KDM5B inhibitors will offer a deeper insight into the therapeutic potential for many types of cancers." (PMID 32751840, 2020). "To test this hypothesis, we first analyzed the differential expression of histone demethylase KDM5B in all cancers in The Cancer Genome Atlas (TCGA) database through Gene Expression Profiling Interactive Analysis (GEPIA) online website (see text Footnote 3)." (PMID 33304897, 2020). "It would be interesting to test how PDK1 affects markers of cancer persisters, such as KDM5B and NGFR, and whether the knockdown cells are still capable of stochastic phenotypic switching." (PMID 32483452, 2020). "However, this particular function of KDM5B in cancer persisters still remains ambiguous, even though KDM5B expression is shown to correlate with dependency on oxidative phosphorylation." (PMID 32483452, 2020). "Therefore, DNA damage repair machinery failed to resolve the damage leading to increased radiosensitivity of KDM5B-overexpressing cancer cells." (PMID 33245716, 2020). "Identification of molecules targeting the KDM5B enzyme could be a potential lead in cancer research." (PMID 32751840, 2020). "Similarly, numerous studies have reported the oncogenic role of KDM5B, where gene expression levels were related with poor prognosis, cancer cell proliferation, and metastasis." (PMID 32751840, 2020). "The regulation of the expression of the pluripotency regulators by CDK1 and KDM5B prompted us to investigate whether the cancer stem cell population is regulated by CDK1 and KDM5B." (PMID 31776402, 2019). "The conflicting reports on KDM5B action in cancer cells may be attributed to KDM5B target genes and interacting partners, which play diverse roles in development, differentiation, and the cell cycle." (PMID 31776402, 2019). "shRNA knockdown of KDM5B inhibits proliferation of several cancer cell lines and xenograft models." (PMID 31776402, 2019). "Finally, our results clearly indicate that KDM5B is one potential molecular target for developing anti-cancer drugs." (PMID 30344945, 2018).
cancer (continued). "Gene amplification of both KDM5A and KDM5B were found in various human cancers." (PMID 30080846, 2018). "KDM5B appears to be an ideal target for the development of anti-cancer drugs." (PMID 30344945, 2018). "The revelation that KDM5B is an H3K4 demethylase indicated that active removal of H3K4 methylation may lead to cancer." (PMID 27974677, 2017). "KDM5B depletion induced cellular senescence and suppressed cancer cell growth." (PMID 27974677, 2017). "Our results on the interaction of TCA cycle-related metabolites with isolated KDM5B reveal the potential for its inhibition by some, but not all, of the tested compounds, including D-2HG, levels of which are elevated in cancer cells due to mutations to IDH1/2." (PMID 28827149, 2017). "Therefore, much research is still needed to discover effective inhibitors that target KDM5B for the prevention and treatment of human cancers." (PMID 27974677, 2017). "Based on the role of KDM5B in cancer stem cell-like events such as cell fate determination, self-renewal and enhanced cell motility, we hypothesized that KDM5B is actively involved in the highly metastatic phenotype of TNBC cells." (PMID 26917489, 2016). "However, KDM5B levels were found to be up-regulated in a variety of human cancers such as bladder cancer, lung cancer, colorectal cancer, prostate cancer, gastric cancer, glioma, ovarian cancer and malignant melanoma." (PMID 26911146, 2016). "JARID1B/KDM5B/PLU1, the H3K4me3/2 demethylase, is frequently elevated in advanced PCa and associated with multidrug resistance, underscoring its potential oncogenic roles in cancers." (PMID 25596733, 2015). "NCOA2, KDM1A, KDM4A, KDM5B and MED1 are AR coregulators implicated in prostate and other cancers." (PMID 26461474, 2015). "Previously, we have shown that KDM5B/PLU1/JARID1B played an important role in EMT of cancer cells." (PMID 25542019, 2014). "Human KDM5A and KDM5B are overexpressed in many forms of cancer." (PMID 25329053, 2014). "Unlike dysregulation of KDM5A and KDM5B that are linked to cancer, mutations in KDM5C are found in patients with syndromic and non-syndromic intellectual disability." (PMID 25329053, 2014). "We study the histone demethylase Jarid1b (Kdm5b/Plu1), as it has been reported to be highly expressed in several human cancers and therefore might present a novel target for anti-cancer therapies." (PMID 23637629, 2013). "Further studies will explore the pan-cancer therapeutic potential of KDM5B inhibition." (PMID 20226085, 2010). "As significant high expression of KDM5B was only observed in cancer cells, and its knockdown suppressed the growth of cancer cells, it may be an ideal druggable molecular target." (PMID 20226085, 2010). "However, our results using several cancer cell lines strongly support the possible involvement of KDM5B in the growth of cancer cells." (PMID 20226085, 2010). "Further functional studies of KDM5B will provide useful information for development of demethylase inhibitors that might show a great promise as a new type of molecular targeted-cancer drugs, as well as HDAC inhibitors." (PMID 20226085, 2010). "Notably, serving as an independent prognostic indicator for LC, elevated KDM5B expression may contribute to the proliferation of cancer cells by modulating H3K4me3 levels in LC." (PMID 39039611, 2024). "Thus, KDM5B may function as a promising target for cancer immunotherapy and the combination of KDM5 inhibitors and STING agonists could maximize the antitumor immune response." (PMID 38769556, 2024). "In normal adult tissues, KDM5B shows a highly restricted expression, except in the testis, where it may contribute to transcriptional control during spermatogenesis, suggesting that it could belong to the class of testis/cancer antigens." (PMID 36697763, 2023). "Drugs targeting KDM5A and KDM5B could be explored as a novel approach to treating some cancers." (PMID 36509829, 2022).
cancer (continued). "Thus, either KDM5A or KDM5B could fulfil the same function in cancer development/drug resistance, depending on the cell context." (PMID 34184733, 2021). "Hence, drugs that can selectively inhibit KDM5B could be of substantial importance as a therapeutic intervention for such cancer types." (PMID 32751840, 2020). "Inhibition of KDM5B may affect apoptosis and reduce growth of cancer cells." (PMID 20226085, 2010). "Given the oncogenic role of KDM5B in BC, using KDM5B as an antigen to stimulate CD8 + T cells and induce cytotoxicity against cancer cells is a potential antitumor immunotherapy approach." (PMID 38769556, 2024). "A combination of keywords and appropriate terms for each database was employed, including “entecavir”, “chronic hepatitis B”, “antiviral drug”, “KDM5B”, “oncology”, “PARP”, “cancer”, “drug repurposing”, and “high genetic barrier”, among others." (PMID 38004468, 2023). "MiR-29a also plays a significant role in promoting apoptosis via several effectors including MCL-1, KDM5B, QKI-6, MMP2, and TNFR1 in various cancers." (PMID 37684602, 2023). "Amplified demethylases with the highest prevalence, above 10% in basal cancers, included H3K4 demethylases KDM5A from locus 12p13.33 and KDM5B from 1q32.1 and H3K9 demethylase KDM4C from 9p24.1." (PMID 37504297, 2023). "This included the lncRNA/coding pair, PCAT6/KDM5B, and the coding/lncRNA pair, LHX1/LHX1-DT, which functions in malignant tumor cell growth." (PMID 37684517, 2023). "Nonetheless, further studies are required to confirm the specificity of Rh(III) complex 1 on KDM5A over KDM5B, KDM5C, KDM5D, or other lysine demethylases in other cancers to fully assess their potential in cancer treatment." (PMID 36509829, 2022). "Since KDM5B was identified as being upregulated in breast and prostate cancer, this member of the KDM5 family has been widely studied in these cancers." (PMID 35406676, 2022). "While it is abundantly clear that KDM5A, KDM5B, and KDM5C can be over expressed in multiple cancers, defining their individual and separate roles in oncogenesis presents a problem." (PMID 35406676, 2022). "KDM5B, has been—and is—the most widely studied KDM5 protein in cancer, and several reviews covering KDM5B are also in print." (PMID 35406676, 2022). "Another interesting histone methylaseis KDM5B, also termed JARID1B, is crucial for inducing an epithelial–mesenchymal–transition of cancer cells." (PMID 35903898, 2022). "Currently, several histone modification regulators, including DOT1L, DNMT1, EZH2, and KDM5B, have been reported to play a role in the TGFβ-stimulated ZEB2 transcriptional upregulation of many cancers." (PMID 35606881, 2022). "Since ZNF217 can also form a complex with KDM5B, it is possible that interactions of KDM5B or other KDMs with ZNF217 occurs in other cancers." (PMID 35406676, 2022). "In myeloid malignancies KDM5A and KDM5B show enzymatic activity towards H3K4me3 while little is known about KDM5C and KDM5D in this context." (PMID 34944554, 2021). "In vitro overexpression of ZEB1 in therapy-naive cells results in downregulation of MITF, upregulation of cancer stem cell markers (e.g., NGFR and lysine demethylase 5B, JARID1B) and mesenchymal markers (e.g., VIM), and increased resistance to MAPKi." (PMID 32796736, 2020). "KDM5B exerts its oncogenic function by inactivating PTEN transcription and by silencing KDM5B, which, remarkably, hinders cancer cell proliferation through p15 and p27 up-regulation." (PMID 32751840, 2020). "JARID1B, also known as PLU1 or KDM5B, is a H3K4me3 histone lysine demethylase identified as an oncogene that is overexpressed in many cancer types." (PMID 31191243, 2019). "Studies support the role of KDM5B (JARID1B, PLU1) as an oncogene since shRNA knockdown of KDM5B inhibits proliferation in several cancer cell lines and xenograft models." (PMID 31805991, 2019). "Inhibition or depletion of KDM5B and KDM5C led to increased STING expression in a wide range of cancer cells." (PMID 30080846, 2018).
cancer (continued). "It has been discovered in research on MDA-MB-231 that KDM5B regulates MDA-MB-231 as a carcinogenic gene and the downregulation of KDM5B leads to lower expression of MALAT1 while decreasing invasion of cancer cells." (PMID 30459529, 2018). "The small molecule inhibitor of KDM5B, EPT-103182, has yielded promising results with anti-proliferative effects in various cancer cell lines and anti-tumour effects in mouse cancer models." (PMID 28536364, 2017). "KDM5B, a member of the KDM family, catalyzes H3K4me2/3 demethylation through transcriptional repression and is involved in DNA repair, drug resistance, and cancer immunotherapy." (PMID 39039611, 2024). "Besides, patients with higher KDM5B levels in GBM usually have poorer overall survival rates and can promote cancer cell proliferation by regulating p21 expression." (PMID 37220590, 2023). "In addition, the down‐regulation of KDM5B in TNBC inhibits long non‐coding RNA MALAT1, thereby inhibiting cancer cell invasion." (PMID 37220590, 2023). "Specifically, KDM5B is a master regulator of H3K4-methylome in stem cells, development, and cancer." (PMID 36697763, 2023). "Here, we describe a previously predicted, but never experimentally characterized, KDM5B isoform that is differentially expressed in different cancer cell lines." (PMID 36697763, 2023). "Since most of the chromatin regulators described here (LSD1, PRMT7, SETDB1, KDM5B, and ATF7IP) converge functionally, it will be crucial to identify additional cancer-specific factors the targeting of which may be less toxic." (PMID 36497341, 2022). "Recent studies reported that targeting epigenetic mechanisms in cancer cells, including DNA methylation by DNMTs, histone methylation, and demethylation by SETDB1, LSD1, and KDM5B could derepress ERVs transcription and lead to induction of interferon response." (PMID 36323669, 2022). "As PCa is also a hormone-driven, luminal-type cancer with significant cellular heterogeneity and CTH, KDM5B might play similar functions in PCa." (PMID 33245716, 2020). "KDM5B, also called JARID1B or PLU1, is a Jumonji C-containing (jmjC) histone lysine demethylase that plays important roles in organogenesis, stem cell functions and cancer development." (PMID 33245716, 2020). "Here, we provided evidence that KDM5B was frequently up-regulated in HCC tissues and that its expression in HCC cells is required to repress the transcription of multiple CDKIs and to maintain sustained proliferation of cancer cells." (PMID 26911146, 2016). "KDM5B, a member of the KDM5 family of proteins, has recently been shown to possess H3-K4 demethylase activity and exhibit oncogenic activities in several human cancers." (PMID 26911146, 2016). "To further assess the mechanism of growth suppression induced by KDM5B knockdown, we performed a flow cytometry to analyze the cell cycle status of cancer cells of cells with or without KDM5B depletion." (PMID 26911146, 2016). "We observed strong KDM5B staining in cancer tissues and no significant staining in non-neoplastic tissues." (PMID 20226085, 2010). "The trend is not as clear for demethylase, but we note that KDM5B, which removes the activating mark H3K4me3, is significantly overexpressed in five of the eight cancer types studied and never repressed, while the H3K27me3 demethylases KDM6A/B are repressed in most cancer types." (PMID 25484917, 2014).